IL13 (interleukin 13)
Diseases named in the same sentence as IL13 in open-access papers (continued):
Sharing a sentence is not in itself a finding about the gene and the disease.
asthma (continued). "In a mouse model of asthma, suppression of HIF‐1α with YC‐1 reduced expression of IL‐5, IL‐13, myeloperoxidase (MPO) and inducible nitric oxide synthase (iNOS), which alleviated asthma symptoms." (PMID 32633061, 2020). "DA treatment effectively inhibited methacholine responsiveness, inflammatory cell infiltration, proinflammatory cytokines such as interleukin (IL)-5 and IL-13, and immunoglobulin (Ig) E in OVA-induced asthma model." (PMID 30991656, 2019). "In an asthma model, TSLP can upregulate natural killer T cells to increase IL-13 production and decrease airway hyperreactivity." (PMID 31284537, 2019). "The anti-IL-25 antibody significantly reduced the levels of IgE, IL-5, and IL-13; goblet cell hyperplasia; and eosinophil infiltration, and prevented AHR in murine asthma models." (PMID 31284537, 2019). "In this study, we demonstrated that anti-Dectin-2 MoAbs considerably inhibit HDM-induced IL-5 and IL-13 production in DC- and monocyte-depleted PBMC co-cultures of patients with asthma." (PMID 31861989, 2019). "The precursors of ASHMI, MSSM-002, inhibit Group 2 cytokines (the inhibition of IL-4, IL-5, IL-13, and GATA-2 and the enhancement of IFN-γ expression) to relieve asthma symptoms." (PMID 31284537, 2019). "The T helper 2 cytokine IL-13 is thought to be the main inducer of goblet cell hyperplasia and MUC5AC production in murine models of asthma, through activation of STAT6." (PMID 30764493, 2019). "The data confirmed that in addition to the effects of improving asthma symptoms, SCIT reduced the proportion of ILC2 in the peripheral blood of children with asthma and downregulated the level of IL-13, a cytokine secreted from ILC2 cells among others." (PMID 31737687, 2019). "Genetic deletion of the IL-33 receptor in a mouse model of experimental asthma increased TSLP production, which stimulated the emergence of IL-13+ ILC2s and lung mast cells leading to airway hyperresponsiveness." (PMID 31866859, 2019). "The antiasthma simplified herbal medicine intervention (ASHMI) alleviates asthma symptoms by modulating Group 1 cytokine (inhibition of TNF-α and IL-6) and Group 2 cytokine (inhibition of IL-17, IL-13, IL-5, and IL-4, and enhancement of IFN-γ) expression." (PMID 31284537, 2019). "When considering the pathophysiology of respiratory diseases such as asthma or COPD, interleukins, especially IL-4, IL-13, IL-1β, and IL-17, are the major inflammatory instigators." (PMID 30744098, 2019). "Nevertheless, these data appear contradictory to previous reports suggesting that TMEM16A plays a key role in mucus production, namely, in asthma where both TMEM16A and MUC5AC are concomitantly up-regulated by IL-4 or IL-13 induction." (PMID 31732694, 2019). "Therefore, IL-13 may be a potential therapeutic target in the treatment of asthma." (PMID 31395084, 2019). "We also observed significant decreases in IL-13 secretion and OVA-specific IgE production in hSF-exposed asthmatic female mice (center and right, **P < 0.01 and *P < 0.05 versus OVA asthma group)." (PMID 30677748, 2019). "IL-13-expressing ILC2 and Th2 cells are also responsible for bronchial epithelial tight junction barrier leakiness in asthma patients." (PMID 31443563, 2019). "Higher levels of several Th2 cytokines have been found in BAL of asthmatics, including IL-4, IL-5, IL-13, IL-25, IL-33, and TSLP, and the levels of Th2 cytokines correlate with severity of asthma exacerbation." (PMID 30764493, 2019). "In the context of asthma associated with Th2 responses, it is possible that recruited NK cells will produce IL-4, IL-5, and IL-13 over IFN-γ, contributing therefore to both the pathology of asthma and impaired antiviral responses." (PMID 31167464, 2019). "In the IL-33-induced asthma model, coadministration of PGE2 or PGE1-alcohol resulted in diminished IL-5 and IL-13 production, reduced eosinophilia and alleviated lung pathology." (PMID 29593738, 2018).
asthma (continued). "Asthma is characterized by an expansion of CD4+ helper T lymphocytes (Th2, Th17), increased production of the Th2 cytokines IL-4, IL-5, and IL-13, an increased level of allergen-specific immunoglobulin E (IgE), eosinophilia and inflammation of the airways." (PMID 30622536, 2018). "For this purpose, we determined differential leukocyte counts and concentrations of IFN-γ, IL-5, IL-6, IL-13, and KC/CXCL1 in BALF in a mouse model of OVA-induced asthma." (PMID 29882826, 2018). "Th1 cells exert a protective effect on asthma through releasing IFN-γ and IL-2, while Th2 cells mainly secrete IL-4, IL-5, and IL-13, and then promote the development of asthma." (PMID 30089474, 2018). "We found that the frequencies of GATA3+IL-4+, GATA3+IL-5+, and GATA3+IL-13+ CD4+ T-cells in the lungs of asthma-induced Bcl11bfl/fl dLck-iCre mice were reduced, as were the frequencies of GATA3+, IL-4+, IL5+, and IL-13+ CD4+ T-cells." (PMID 29700302, 2018). "The “Th2-dependent” inflammatory subtype of asthma or CRS is mediated to a large extent by IL-4, IL-5, and IL-13 cytokines." (PMID 29707206, 2018). "In murine models of asthma, CD4+ T-helper cells in the lungs and bronchoalveolar lavage fluid decrease eosinophilia and the Th2 cytokine secretion of IL-4, IL-5, IL-13, and TGF-β." (PMID 29959403, 2018). "Nearly 100 asthma-related genes have been identified using GWAS, such as IL33 on the 9p24 chromosomal region, HLA-DR/DQ on 6p21, IL1RL1/IL18R1 on 2q12, and IL13 on 5q31." (PMID 29751569, 2018). "Associations were found in the current childhood asthma GWAS with known asthma loci in IL1RL1, IL13, LINC01149, near GSDMB, and in the C11orf30-LRRC32 region (Bonferroni adjusted p < 0.05 for all comparisons)." (PMID 30373671, 2018). "The data showed that resveratrol significantly reduced IL-5, IL-13, and TGF-β in the serum and BALF in mice with OVA-induced asthma." (PMID 30619345, 2018). "Lung resident type 2 innate lymphoid cells (ILC2) have been shown to function as a potential early source for IL-5 and IL-13, and are supposed to contribute to allergen-independent AHR and asthma." (PMID 29678672, 2018). "The CD4+ T cell is a dominant activated T cell subtype in clinical allergic asthma and in animal models of asthma, an mainly contributes to AHR development and allergic inflammation by secreting Th2 cytokines such as IL-4, IL-5, and IL-13." (PMID 29910732, 2018). "Although these inhibitors have shown minimal benefits for asthma in clinical trials, knocking-out all of the NOS isoforms decreases airway inflammation and reduces Th2 cytokines such as IL-4, IL-5, and IL-13 in asthmatic mice." (PMID 29302700, 2018). "Therefore, IL-4 and IL-13 may be key factors in suppressing the induction of asthma." (PMID 29151835, 2017). "Sec14-like 3 (Sec14l3) - a putative target of Creb1 - was down-regulated in both asthma models and in NHBE cells upon IL13 treatment, while it’s expression correlated with ciliated cell development and decreased along with increasing goblet cell metaplasia." (PMID 28383034, 2017). "First, Wyeth evaluated the efficacy of two separate humanized anti-IL-13 IgG1 monoclonal antibodies (IMA-638 [NCT00339872]; IMA-026 [NCT00725582]) in asthma clinical trials." (PMID 28721208, 2017). "Higher expression of Th2-driven cytokines (IL-4, IL-5, IL-9, and IL-13), TSLP, IL-25 and IL-33 in nasal tissues was observed in severe asthma." (PMID 28199345, 2017). "We found that BPIFA1 levels were significantly diminished in sputum derived from asthma patients and that a similar decrease in BPIFA1 levels was observed in apical secretions from both asthmatic and IL-13-exposed HBECs." (PMID 28165446, 2017). "The IL-13 response signature (CLCA1, POSTN, SERPINB2) was also upregulated in the central airways in severe asthma compared to health, however, to a lesser extent compared to peripheral airways, and it did not attain significance." (PMID 28045928, 2017).
asthma (continued). "In particular, Doganci and colleagues found that local blockade of the sIL-6R in an ovalbumin mouse model of the late-phase asthma response reduced eosinophil numbers in BALF and decreased levels of the Th2 cytokines IL-4, IL-5, and IL-13." (PMID 28334838, 2017). "Furthermore, sputum IL-13 levels could serve as a useful biomarker for asthma control assessment." (PMID 28057889, 2017). "Gene silencing of CD86 by siRNA also decreased airway eosinophilia, BAL fluids IL-5 and IL-13, and CCL17 production, serum OVA-specific IgE levels, and AHR in an OVA-induced mouse asthma model." (PMID 28106744, 2017). "Indeed, the need for new biomarkers of inflammation in asthma has been highlighted in a recent study of an IL-13 neutralising monoclonal antibody, where measurement of airway IL-13 levels might be a more relevant biomarker than blood eosinophils and serum periostin." (PMID 28373098, 2017). "The levels of inflammatory factors (IL-5, IL-6, IL-13, and TNF-α) and those of fibrosis-related proteins (basic fibroblast growth factor (bFGF), IGFBP-3, and TGF-β) were significantly higher in asthma patients than in healthy controls." (PMID 28796252, 2017). "Concentrations of IL-4 (23.40 ± 0.78 pg/mL), IL-5 (15.05 ± 1.13 pg/mL), IL-13 (331.93 ± 61.74 pg/ml), IL-17 (72.21 ± 7.10 pg/ml) in BALF of mice in the wild-type group with asthma were significantly higher than that of control group (P < 0.05)." (PMID 28094276, 2017). "Conversely, in severe asthma with CRS, Th2-derived cytokines of IL-4, IL-5, and IL-13 were markedly expressed in the epithelium, endothelium, subepithelial infiltrating cells, and mucus glands (respectively)." (PMID 28199345, 2017). "In previous studies, IL-13 has been reported to increase CD44 and CD44 isoform expression in a murine model of asthma and in colon epithelial cells, respectively." (PMID 27533463, 2016). "Airway inflammation is a key component of asthma and of the OVA-sensitization model and is characterized by the presence of granulocytes and increased levels of Th2 cytokines such as IL13, IL4 and IL5." (PMID 27820848, 2016). "Daily oral administration of WGP (400 μg) significantly reduced pulmonary eosinophil influx and production of Th2 cytokines (IL-4, IL-5, IL-13), however serum IgE levels were unaffected by WGP treatment in an OVA-induced asthma model." (PMID 27390655, 2016). "The effect of dexamethasone varied between cytokines, with IL-17 being inhibited less than IL-13 and IFNγ (ANOVA analysis in healthy subjects and asthma; p = 0.0002 and p = 0.0006 respectively)." (PMID 27716212, 2016). "In this study, in order to investigate the correlation among IL-25, IL-5, IL-13 and nuocyte activities, we used OVA-sensitization and -challenging to induce the mouse model of asthma." (PMID 27617447, 2016). "Asthma symptoms are related to the presence of activated Th2 cytokine-producing cells (IL4, IL5, IL9 and IL13) in the airway wall." (PMID 26986948, 2016). "In the field of asthma research, one study revealed that DPP4 mRNA expression was induced by IL-13 stimulation of normal human BECs by microarray analysis but it did not examined DPP4 in detail." (PMID 26975422, 2016). "Serum IL-31 levels correlated positively with Th2 related cytokines (IL-5, IL-13, and TSLP), asthma severity or total serum immunoglobulin E (IgE), and inversely with asthma control and the forced expiratory volume in 1 second (FEV1)." (PMID 26956917, 2016). "We found that the serum levels of IL-5, IL-13 and TSLP were significantly elevated in patients with asthma compared with controls." (PMID 26956917, 2016). "It is well known that inflammatory mediators such as IL-4 and IL-13 as well as the persistence of chronic inflammation in airways are involved in the remodeling process, so natural compounds that inhibit the inflammatory process in asthma may also prevent the remodeling process." (PMID 27445433, 2016).
asthma (continued). "It should be noted that we stained only for IL-13, and therefore we cannot exclude an increase in TH2 cells secreting IL-4 or IL-5 in the more severe asthma clusters." (PMID 25746968, 2015). "CLCA1 is a promising therapeutic target for asthma and COPD, as it is the only member of its family to be upregulated in models of IL-13 mediated mucus overproduction, is a secreted protein, is expressed in goblet cells, and associates with mucin granules." (PMID 26612971, 2015). "The cross-regulation of IL-13 and IFN-γ has been well established in in vitro and in vivo models of asthma and IL-13 has been shown to be protective to epithelium in vitro." (PMID 25889094, 2015). "Data collected from people with asthma and also in mouse models of asthma driven by inhalation of the model antigen ovalbumin (OVA) have shown that IL-4, IL-5, and IL-13 have potential to serve as an allergic asthma biomarker profile." (PMID 26346739, 2015). "In the study on the murine asthma model, acidic mammalian chitinase (AMC) was found to be upregulated and its expression was induced by cytokines IL-4 and IL-13." (PMID 25663327, 2015). "Those are related to asthma and immune responses and include CCL8, CCL11, CCL24, IL4, IL6, IL10, IL13, IL1β, TNFą, and others." (PMID 26052354, 2015). "In addition, ATF3 directly binds to CRE sites in the IL-4, IL-5 and IL-13 promoter regions and ATF3 binding sites were found enriched in a recent epigenomic analysis of regulated genes that play a role for TH2 memory cell differentiation and asthma susceptibility." (PMID 26459392, 2015). "By contrast, compared to Neu-Normal asthma, Neu-High asthma had higher IL-8 levels (p<0.01) and lower % predicted FEV1 (p<0.01), but similar levels of eosinophil %, IL-5, IL-13, IL-16, and PDGF-bb and other cytokines and chemokines (data not shown)." (PMID 26011707, 2015). "Asthma historically was characterized as being a CD4+ TH2-mediated disease with increased production of IL-4, IL-13, and IL-5." (PMID 25772594, 2015). "The current study aimed to investigate the expression of IL-4 and IL-13, as well as IL-6, IL-10 and TNF-α, in the sheep model of asthma following allergen challenge of the airways." (PMID 26362930, 2015). "Focussing on genes of the Th2 pathway (IL4, IL4R, IL13, GATA3, STAT6), the authors demonstrated that the odds of asthma tended to decrease at the age of 10 years with increasing GATA3 methylation." (PMID 26052354, 2015). "Instead of the commonly used animal model of asthma induced by OVA, our mouse model showing increased eosinophils and high expression of IL-4, IL-5 and IL-13 detected in BALF and lung tissue is considered to bear a closer resemblance to human asthma." (PMID 24671176, 2014). "In our model of asthma SOCS3-siRNA treatment produce also a decreased expression in IL-5, IL-13, and IL-4." (PMID 24637581, 2014). "Studies in other models (asthma, trauma) demonstrated that Th1 cytokines such as IL-2 and IFN-gamma were increased whereas Th2 cytokines such as IL-4, IL-10 and IL-13 were suppressed." (PMID 24732949, 2014). "In a Phase II clinical study of subjects with uncontrolled asthma, despite inhaled corticosteroids (ICS), it was demonstrated that periostin status predicted the response to an anti-IL-13 monoclonal antibody, lebrikizumab." (PMID 24146092, 2014). "The lungs of T-bet-/- mice have been reported to display spontaneous airway remodeling, subepithelial collagen deposition, IL-13 mediated airway hyper-reactivity (AHR) and eosinophil infiltration, similar to an asthma-like phenotype." (PMID 24499286, 2014). "Our data shows that overproduction of IL-18 protein in the lungs increases pulmonary inflammation accompanied with IL-13 producing CD4+ T cells, and results in increasing AHR in this mouse asthma model." (PMID 23382928, 2013).
asthma (continued). "Both in vivo and in vitro studies confirmed that Vitamin A and ATRA induce Th2 bias and promote Th2 cytokines realise, such as IL-4, IL-5, IL-13 and GATA-3, which is one of the major characteristics of asthma." (PMID 24204796, 2013). "The results lead us to suggest that Abl expression in smooth muscle does not modulate inflammatory cell infiltration and production of IL-13 and CCL2 in asthma." (PMID 24112389, 2013). "Although both cytokines share receptor subunits, IL-4 and IL-13 have differential roles in asthma pathogenesis: IL-4 regulates TH2 cell differentiation, while IL-13 regulates airway hyperreactivity and mucus production." (PMID 23940740, 2013). "Thus, an important contribution of IL-9, in asthma, may instead be on epithelial integrity and ciliated cell number and function, leading to impaired mucus clearance, particularly in severe disease, something that can be said of IL-13 as well." (PMID 23671562, 2013). "Th2 cytokines IL-13 and IL-4, which were overexpressed in the OVA-induced asthma model, were suppressed by both doses of ACA." (PMID 23451048, 2013). "In mild asthma, Il10 showed the largest change in expression followed by II5, II4, Tnfα, Il6, Il2, Il13, and Ifnγ, respectively." (PMID 23781124, 2013). "Previously, IL-13 was known to be a key mediator of AHR development and goblet cell hyperplasia in an OVA-sensitized asthma model." (PMID 23855490, 2013). "We previously demonstrated that simvastatin ameliorates allergic eosinophilic airway inflammation, decreases IL-13 and IL-4 levels in lung lavage fluid, and improves airway hyperreactivity (AHR) in the ovalbumin mouse model of asthma." (PMID 22583375, 2012). "Home dampness combined with each one of the genes STAT6, IL13 and ADRB2 raised the testing accuracy on asthma higher than 57.34%." (PMID 22355322, 2012). "IL-13 stimulation can induce CLCA1 and MUC5AC expression in normal human bronchial epithelial cells and murine asthma models." (PMID 22731784, 2012). "A number of biological agents have been developed to target cytokines thought to play an important role in asthma pathogenesis, including monoclonal antibody blockers of TNF-α, IL-5, IL-4 and IL-13." (PMID 21896202, 2011). "HDM-induced cytokine expression of IL-5, IL-9, IL-10, IL-13, and IFN-γ were significantly elevated in teens with asthma." (PMID 21655126, 2011). "Asthma is characterized by chronic inflammation in the airways and the presence of a predominance of CD4+ T-helper 2 cells that secrete IL-4, IL-5, and IL-13 cytokines." (PMID 21655126, 2011). "Percentage proportions of CD4+ T cell staining positively for IL-2, IL-4, IL-10, IL-13, IFN-γ, and TNF-α in unstimulated whole blood were similar in children with asthma compared to healthy controls." (PMID 21197090, 2010). "In asthma, CCR8 was expressed by 30.3±3.0% and 28.9±7.8% of the IL-4+- and IL-13+-producing BAL CD3+ cells, respectively." (PMID 20455898, 2010). "The data for IL-2-stimulated accumulation of IL-13+ and IFN-γ+ T cell accumulation were stratified to demonstrate the contributions of gender and asthma on accumulation." (PMID 20667106, 2010). "In contrast to the effects of IL-4 and IL-13, inhalation of IFN-γ decreases eosinophilic inflammation in the airways of subjects with asthma and treatment of mouse airways with IFN-γ inhibits eosinophilic airway inflammation." (PMID 20953328, 2010). "In contrast, neutralisation of IL-13 has been shown to reduce AHR to inhaled spasmogens in mouse and sheep models of asthma." (PMID 20957211, 2010). "Preliminary results with a murine asthma model suggest that Retnla also suppresses the development of AHR, which is consistent with the suppression of IL-13 responses by Retnla." (PMID 19381262, 2009). "When analyzing asthma instead of wheezing, the interaction between ETS-2 and IL13 haplotype pairs was statistically significant (p = 0.03) for persistent asthma as it was for persistent wheeze." (PMID 18186920, 2008).